ALK (ALK receptor tyrosine kinase)
Diseases named in the same sentence as ALK in open-access papers (continued):
Sharing a sentence is not in itself a finding about the gene and the disease.
tumor (continued). "Six of 10 pts enrolled with untreated or progressing brain metastases showed response in brain, including 4 with complete resolution; 2 stable disease, 2 progressed; AP26113 has promising anti-tumor activity in pts with crizotinib-resistant ALK+ NSCLC, including pts with brain metastases." (PMID 25888090, 2015). "At the time of the second surgery, molecular analysis was performed to investigate whether the tumour possessed the ALK fusion gene." (PMID 25788996, 2015). "Compelling studies have indicated that all these malignancies are partially or fully dependent on ALK kinase activity for proliferation and survival, as inhibition of ALK or downregulation of its expression yields potent anti-tumour efficacy both in vitro and in vivo." (PMID 25874976, 2015). "EGFR up-regulation has also been observed in ALK positive tumor cell lines resistant to crizotinib." (PMID 25888090, 2015). "The potential role of miRNAs in the modulation of tumor immunophenotype and microenvironment offers an exciting hypothesis to understand the biology of ALK+ ALCL." (PMID 25688981, 2015). "Others suggested that IMTs are true neoplasms based on the role of oncogenic viruses and cytogenetic abnormalities, including ALK gene rearrangements on chromosome 2p23, clonal chromosome abnormalities and DNA aneuploidy, and occasional aggressive local behavior along with tumor metastasis." (PMID 25688324, 2015). "Using this approach, we were able to isolate DTCs from marrow samples with a tumor cell concentration as low as 0.01%, and demonstrate concordance for ALK status between primary tumor and DTCs for all patients for whom status of the primary tumor had been ascertained." (PMID 25133137, 2014). "We speculated that the percentage of tumor cells with ALK fusion might be very low in these two cases." (PMID 24422905, 2014). "Tissue analysis of harvested tumor cells from patients resistant to crizotinib has demonstrated other non-gatekeeper secondary mutations in the ALK TK receptor." (PMID 25101240, 2014). "To do this, we used cell line spiking experiments at concentrations of 1 tumor cell in 106 WBCs for two different cell lines, Kelly and NB1643M (a sub-clone of the NB1643 cell line, which is homozygous for the R1275Q mutation in the ALK gene)." (PMID 25133137, 2014). "While a direct involvement of the cancer-related oncogenes ALK in 2p23.2, MLLT3 in 9p21.3, and BCL2 in 18q21.33 could be excluded, loss of two tumor suppresser gene loci in 9p21 and in 13q14 was found." (PMID 25374696, 2014). "Also, ALK amplifications have been described in several tumor types, leading to the presence of multiple copies of the wild-type full-length ALK gene." (PMID 25593912, 2014). "Given the fact that ALK+ ALCL exhibits high levels of apoptosis and is typically responsive to conventional chemotherapy, we examined whether GzB expression might play a role in sensitizing ALK+ ALCL tumour cells to apoptosis." (PMID 25168906, 2014). "Presently it is unclear if these ALK “kinase dead” mutations promote tumor growth or are “passenger mutations” that do not effect cell proliferation." (PMID 24955213, 2014). "The tumor was also ALK positive by IHC and the patient responded to crizotinib therapy." (PMID 24955213, 2014). "It is probable that ALK+ ALCL tumours have not acquired many secondary oncogenic mutations/alterations that would be predicted to render these tumour cells less susceptible to chemotherapy." (PMID 25168906, 2014). "Interestingly, ALK-F1174L expression in MONC-1 cells not only strongly accelerated tumor growth, but also affected their differentiation capacity." (PMID 24947326, 2014). "Therefore, in order to detect the fusion in the ATC tumor, we performed an ALK specific reverse transcription using an ALK reverse primer followed by PCR." (PMID 24475247, 2014). "Notably, ALK rearrangement was more common in poor tumor differentiation in our selected population." (PMID 24404167, 2014).
tumor (continued). "Moreover, compared with NSCLC patients with tumor stage IV, ALK rearrangements were underrepresented in those with tumor stage I–III (OR = 0.58; 95% CI: 0.44–0.78; P = 0.0002)." (PMID 24959902, 2014). "IHC staining (Clone 1A4, Origene, 1:200) showed tumor cell positivity for ALK protein." (PMID 24885608, 2014). "Furthermore, all CTCs harbored a unique ALK-rearrangement pattern consisting in the 3′5′ break apart of ALK probes whereas heterogeneous rearrangement patterns were present within the tumor." (PMID 25414829, 2014). "It is possible that this treatment is effective for tumor cells resistant to ALK inhibitors." (PMID 24842630, 2014). "Given the implicated role of ACK-1 in EGFR, KRAS and ALK signaling, we suggest a potential therapeutic niche for combination studies with bosutinib selecting for patients with ACK-1 overexpression, specifically in circumventing tumor metastasis and recurrence." (PMID 24461128, 2014). "Possibly, NSCLCs carrying different EML-ALK translocations may respond to ALK inhibitor therapy with different sensitivities, patient response rates, and tumor burden reduction characteristics." (PMID 24955213, 2014). "Finding alternatives to a tumor biopsy and more effective means to diagnose an ALK rearrangement is a critical issue in order to identify NSCLC patients who may benefit from an ALK inhibitor treatment." (PMID 25414829, 2014). "In another patient, whole exome sequencing analysis of tumor and normal samples revealed a mutation in ALK (Chr2: 29,551,215; C > T); plasma DNA levels were not analyzed for this patient." (PMID 25516806, 2014). "Thus, in our NCPC models, ALK expression in MONC-1 or JoMa1 cells appeared to maintain tumor cells in an undifferentiated state." (PMID 24947326, 2014). "This is the number of tumor cells that are required for the FDA-approved FISH ALK assay." (PMID 25248157, 2014). "The production of a Tamoxifen-dependent Cre model allowing ALK activation at different development time points, as suggested, could help to determine whether a specific development period exists for NB tumor initiation and progression." (PMID 24947326, 2014). "Indeed, we observed that Myc mRNA downregulation, induced by ALK inhibitor treatment in tumor-derived JoMa1-ALK cells, was concomitant with Mycn upregulation." (PMID 24947326, 2014). "Immunostaining showed that the tumor cells were positive for both ALK and KIT expression, and it was thus difficult to distinguish whether the tumor was an IMT or GIST." (PMID 24938355, 2014). "However, there were no statistical differences in sex distribution, clinical symptoms, primary lesion of the tumor, and Ann Arbor staging between ALK + and ALK- patients (p > 0.05)." (PMID 24112608, 2013). "Although majority (8/13, 61.5%) of the patients with ALK rearrangement were in stage I and none was in stage IV, the association with tumor stage was statistically non-significant (p= 0.5740)." (PMID 23951022, 2013). "In addition, recent reports showed that ALK inhibition in NSCLC patients with the ALK rearrangement resulted in tumor shrinkage or stable disease in most patients." (PMID 23714228, 2013). "Of the 99 tumor samples screened, 13 patients (13.1%) harbored an activating EGFR mutation, 7 patients (7.1%) were ALK positive and 65 patients (65.7%) were EGFR WT and ALK negative, and in 14 patients (14.1%) there was not enough tissue to perform a valid FISH assay for ALK." (PMID 23359795, 2013). "Positive cytoplasmic staining of phosphorylated ALK (pALK) in all tumour nests in BCC was found." (PMID 24163262, 2013). "Taken together, ALK fusion-positive tumours showed similar levels of overall chromosome instability, but when focusing on particular cancer-related regions, significantly fewer copy number gains at oncogene-related loci and significantly fewer deletions at suppressor gene-related loci." (PMID 23289484, 2013).
tumor (continued). "Since FISH has been approved as a reliable diagnostic test for crizotinib (ALK inhibitor) treatment, our findings might suggest that high abundance of EML4-ALK positive cells in tumor tissues could also be related to the treatment response to ALK inhibitors." (PMID 23951022, 2013). "We tested their effects on the phosphorylation of ALK and ALK-driven tumor cell growth." (PMID 24386191, 2013). "However, in 16 (64%) of the 25 samples, we found 3 to 4 extra copies of adjacently placed EML4 and ALK signals in 2-50% of the tumor cells." (PMID 24156086, 2013). "All ALK+ ALCL cases showed a strong nucleolar expression of DDX21 in the tumor cells." (PMID 23741337, 2013). "EMT phenotype is the characteristic finding of ALK-rearranged tumors compared with other genotypes, and this could potentially be a contributing feature to the frequent metastases and high tumor stage seen in ALK-rearranged tumors." (PMID 24194854, 2013). "Also, changes in tumour suppressor gene-related regions, such as 9p21.3 (CDKN2A) 9p23-24.1 (PTPRD), 13q14.2 (RB1), were significantly fewer in tumours with ALK fusion." (PMID 23289484, 2013). "Although germline mutations of ALK and PHOX2B account for the majority of familial NB, additional genetic factors responsible for NB tumor progression may still be discovered." (PMID 24205241, 2013). "Furthermore, at the smaller-genomic scale level, ALK fusion-positive tumours were less amplified at the loci containing EGFR family genes, 7p11.2 (EGFR), 17q12 (ERBB2) and other loci, 1p34.3 (MYCL), 7p21.1, 8q24.21 (MYC), 16p13.3 and 17q25.1." (PMID 23289484, 2013). "When an ALK rearrangement is present in a tumor, whether it is an inversion or translocation, one of the two fusion signals separates as one red and one green signal (arrows)." (PMID 24102046, 2013). "In theory, ALK FISH is capable of detecting any rearrangement involving ALK, regardless of the fusion partners or the EML4-ALK variants, on FFPE tissue which represents the most common method for processing and storing tumor specimens." (PMID 23741400, 2013). "Unfortunately, EGFR-TKI treatment was not effective in the tumor regression nor tumor marker level of present patient (disease might be controlled), but treatment with an ALK inhibitor resulted in SD with decreasing tumor markers." (PMID 23714228, 2013). "Nevertheless the possibility of triggering of the downstream signaling pathways in the tumor cells as a result of the mild increase in copy numbers of the ALK gene with or without underlying chromosome 2 aneusomy needs further investigation." (PMID 24156086, 2013). "ALK fusion positive tumours are speculated to be less dependent on the actions of oncogenes and tumour-suppressor genes induced by copy number changes." (PMID 23289484, 2013). "Moreover, xenograft IBC tumors were resistant to paclitaxel but sensitive to low doses of crizotinib, which resulted in tumor shrinkage similar to that reported in ALK-driven NSCLC models." (PMID 24156086, 2013). "It would require a large case number to determine whether the incidence of ALK rearrangements would increase with the tumor stage, since the incidence of ALK rearrangements was quite low." (PMID 23951022, 2013). "In summary, among the three detection methods for ALK rearrangements, RT-PCR could detect not only the presence of EML4-ALK fusion gene and the variant types, but also the abundance of EML4-ALK positive cells in NSCLC tumor tissues." (PMID 23951022, 2013). "Thus tumors with ALK fusion feature significantly fewer copy number gains and losses at loci containing oncogenes and tumor-suppressor genes, respectively." (PMID 23289484, 2013). "In this case the tumor cells showed a positive immunnoreactivity with ALK protein." (PMID 23374227, 2013). "This suggests a function of ALK in tumour proliferation in human BCC." (PMID 24163262, 2013).
tumor (continued). "Homozygous deletion was seen only at 9p21.3 including CDKN2A and limited to EGFR-mutated tumours among ALK fusion-negative neoplasms as reported in the literature and also seen in ALK-fusion positive ones." (PMID 23289484, 2013). "Cases of atypical translocation with partial loss of chromosomal material, resulting in so called single-red signals by fluorescence in-situ hybridization (FISH) analysis of ALK gene rearrangements in tumor cell nuclei, may also occur." (PMID 24279718, 2013). "At high-power microscopy, the tumor cells were positively stained for ALK." (PMID 23617234, 2013). "Furthermore, this study showed that phosphorylation of GSK-3β on serine 9 correlated with elevated CDC25A levels in ALK+ ALCL patient tumour biopsies." (PMID 22852078, 2012). "Immunohistochemically, the tumor cells were cytokeratin -, vimentin +, CD3+, CD45RO+, CD5-, CD7-, CD4-, CD8-, CD10-, CD20-, CD30-, CD79a-, CD138-, CD56-, granzyme B-, TIA-1 cytotoxic granule-associated RNA binding protein (TIA-1) + and ALK-." (PMID 22931631, 2012). "If a tumor exhibits an unrecognized anti-ALK staining pattern, the patient may have a novel fusion partner." (PMID 22347464, 2012). "In addition, a xenograft model of a human NSCLC cell line containing the ALK rearrangement, tumor regression was observed at clinically relevant doses of IPI-504." (PMID 22928112, 2012). "First, IHC typically shows diffuse ALK expression in ALK-positive tumours." (PMID 22825000, 2012). "Overall, 49 of the 1387 tumor samples (3.5%) had altered ALK signals." (PMID 23198868, 2012). "In a disomic tumour cell with one rearranged ALK gene copy, the probability of detecting break apart signals in the two-dimensional projection may therefore not exceed 25–30 %." (PMID 22825000, 2012). "Therefore, 92% of ALK rearrangements in NSCLC are predicted to occur in patients whose tumours can be proven to be both EGFR and KRAS wild type." (PMID 22374459, 2012). "ALK+ LBCL is an aggressive tumor with a poor response to conventional therapies." (PMID 22474449, 2012). "Additionally, functional studies—such as patient-derived organoids and single-cell sequencing—are essential to elucidate the biological impact of SMAD2, ERBB4, ALK, and CTNNB1 mutations and their roles in tumor heterogeneity, drug resistance, and immune evasion." (PMID 40869017, 2025). "Moreover, there was a strong positive correlation between mice serum RNase1 concentration and tumor size (R = 0.89), raising an interesting notion that RNase1 concentration and phospho-ALK may serve as biomarkers to identify the RDAA positive tumors." (PMID 40246819, 2025). "Additionally, other pathways of the kinase signaling pathway may allow tumor cells to evade the inhibitory effects of ALK-TKIs." (PMID 40584293, 2025). "Overall, next-generation ALK inhibitors, through structural optimization and enhanced pharmacologic profiles, hold the potential not only to overcome existing resistance barriers but also to enable precise modulation of tumor biology, ultimately improving therapeutic efficacy and tolerability." (PMID 41614760, 2025). "Generally speaking, the presented ML pipeline could be deployed for other classification tasks (e.g., classification of EGFR or ALK mutation instead of KRAS, or tumor phenotyping as originally envisioned for radiomics), and besides radiomic features, any tabular dataset could be used or added." (PMID 39860023, 2025). "This suggests that in tumours with high ALK expression but lacking ALK mutations, oncogenic signalling may be driven by microenvironmental ligands such as ALKAL2, potentially derived from the adrenal medulla." (PMID 41511287, 2025). "The tumor microenvironment contributes to therapeutic evasion by establishing a protective niche through fibroblast-derived factors, infiltration of immunosuppressive cells, and extracellular matrix remodeling, thereby attenuating the efficacy of ALK inhibitors." (PMID 41614760, 2025).
tumor (continued). "However, tumor regression was incomplete, and ALK signaling remained largely unaffected." (PMID 40508013, 2025). "It seems that DCTN1, as a fusion partner of ALK, does not predispose one to a specific clinical manifestation, disease course, or histological appearance; however, due to the rarity of this tumor entity, it is crucial to perform a larger study to elucidate this issue." (PMID 40361876, 2025). "This is caused by either genetic factors, i.e., secondary mutations in the ALK kinase domain or amplification of the ALK locus, with tumor cells still being ALK dependent, or nongenetic factors, i.e., activation of bypass signaling pathways and phenotypic changes." (PMID 40524253, 2025). "Another contributing factor is phenotypic switching, where tumor cells may undergo a transformation into small-cell lung cancer with more aggressive features or exhibit epithelial–mesenchymal transition features, leading to the ineffectiveness of ALK-TKIs." (PMID 40584293, 2025). "Therefore, whether ALK activation mediated by ALKAL1/2 contributes to tumor progression still needed to be confirmed by further studies." (PMID 40246819, 2025). "For future investigations, the combination of ALK TKI with merlin re‐activation or downstream inhibition might be crucial for patients with NF2 mutations, particularly if NF2 is found in the baseline tumor." (PMID 40168046, 2025). "Since the CAF-derived secretome was also able to interfere with drug susceptibility in ALK-driven lung tumor spheroids, we hypothesized that a potential link exists between CAF-mediated paracrine signaling and enhanced lipid metabolic activity in tumor cells." (PMID 40524253, 2025). "Importantly, when we tested six other selective ALK inhibitors on our tumor model collection, we found that ceritinib was by far the most efficacious compound, comparably strong to doxorubicin and much stronger than cisplatin, the standard-of-care therapeutics for HB." (PMID 40968384, 2025). "Interestingly, the similarity in survival and mutation status between groups implies that the underlying tumor biology—including molecular drivers like EGFR or ALK—is not significantly impacted by FPMH in this cohort." (PMID 40805843, 2025). "Similarly, PD-L1 expression is elevated in both the tumor and stromal compartments of ALK-TKI resistant tumors, although the exact mechanisms remain unclear." (PMID 40058234, 2025). "Therefore, we hypothesize that dysfunction of the SWI/SNF complex may have a potential impact on MAPK signaling, synergistically enhancing the anti-tumor effects of ALK inhibitors on tumor cell proliferation." (PMID 40416876, 2025). "The tumours classified as MYCN-type showed genomic amplification of MYCN (MNA); however, some MYCN-type cases lacked evident MNA, suggesting that epigenetic states might be influenced by other factors such as activating ALK mutations." (PMID 40713849, 2025). "Notably, depletion of HDAC1 protein or loss of its catalytic activity resulted in significant alterations of the immunophenotype of ALK+ tumor cells, including a higher number of TCRb expressing cells and consequently increased dissemination of tumor cells into distant organs." (PMID 40175628, 2025). "Accordingly, we found that low MELK and ALK mRNA expression is associated with a significantly improved patient RFS rate, depending on whether the patient carries a tumor with the ERα-positive/PR-positive/HER2-negative or the ERα-positive/PR-negative/HER2-positive phenotype, respectively." (PMID 38589728, 2024). "In ALK-rearranged PDTOs, a multiparametric analysis including cancer stage and tumor cell proliferation rate showed that an ALK-directed drug response could be classified according to both the rearrangement status and the clinical data, highlighting its potential in the decision-making process." (PMID 39409152, 2024). "Continuation of ALK TKI while undergoing radiotherapy may increase tumor cell radiosensitivity." (PMID 38835344, 2024).